WT1 (WT1 transcription factor)
Diseases named in the same sentence as WT1 in open-access papers (continued):
Sharing a sentence is not in itself a finding about the gene and the disease.
mesothelioma (continued). "Meanwhile, we demonstrated the increased expression of seven MPM biomarkers including BAP1, EMA, CD141, WT1, D2-40, Calretinin and CK6 in 3D cultured patient mesothelioma cancer cells compared to its 2D counterparts." (PMID 36091141, 2022). "In mesothelioma, positive markers, such as CK5/6, calretinin, WT‐1, HBME‐1, thrombomodulin, mesothelin and D2‐40, are commonly used, and negative markers such as TTF‐1, CEA, MOC31, BG8 and Ber‐EP4 are rarely expressed." (PMID 35950141, 2022). "Epithelial membrane antigen and factor VIII are strongly suggestive for the diagnosis of MM; mesothelioma-related markers include calretinin, thrombomodulin, CK5/6 (pleural), WT1 (Wilms tumour antibody), D2-40, CK7 (tunica vaginalis), CD20 +, and calretinin +." (PMID 31470859, 2019). "In our case, the papillary or large cell population showed a staining pattern characteristic for mesothelioma with calretinin, cytokeratin, and CD99 positivity, while the small cell component was positive for CD99, WT1, FLI-1, and cytokeratin." (PMID 27403364, 2016). "Primary mesothelial cells from WT mice, immortalized cells iMeso-WT1, iMeso-NF3, and mesothelioma cells from the lines AK7 and RN5, all derived from a C57Bl/6J background, were injected (4 × 105 cells) subcutaneously into the right flank of C57Bl/6J mice." (PMID 25877069, 2015). "In mesothelioma, the TAA's mesothelin and Wilms tumour-1 (WT-1) are highly expressed and thought to be physiologically relevant to this tumour type." (PMID 22778767, 2012). "Epithelioid-type MPMs were immunostained with antibodies against intelectin-1 or typical mesothelioma markers, such as calretinin, CK5/6, podoplanin, WT-1, and mesothelin." (PMID 22768319, 2012). "The expression of general mesothelioma markers (mesothelin, cytokeratin 5/6, calretinin, HBME-1, thrombomodulin, and WT-1) in spheroids is consistent with those of mesothelioma specimens." (PMID 22737246, 2012). "Immunohistochemical studies were grossly negative for cytokeratin, calretinin, and WT1, which was inconsistent with the original mesothelioma diagnosis." (PMID 39968515, 2025). "WT1 is usually positive in mesotheliomas, though rare negative cases, such as ours, have been reported." (PMID 41235016, 2025). "Therefore, to identify factors that influenced the immunogenicity of cancer cells, we decided to use mesothelioma cells as target cancer cells, in which MHC-I and the target antigen WT1 are highly expressed." (PMID 39116074, 2024). "The specificity of the TCR could be more accurately assessed if the reactivity of the WT1 epitope-specific TCR was assessed using mesothelioma cells expressing MHC-I, WT1 antigen, and IP, such as MESO-4 and HMMME." (PMID 39116074, 2024). "As expected, high tumor cell MSLN expression coincided with diffuse D2-40 expression by mesothelioma cells because both proteins are located in the cellular membrane, while nuclear expression of WT-1 and BAP-1 showed non-specificity with MSLN." (PMID 37901248, 2023). "Another two cases, both with a predominant pleural tumor mass (patient 4 and 7), were initially classified as mesothelioma, although all mesothelial markers such as calretinin, WT1, D2-40 and CK5/6 tested negative and BAP-1 and MTAP were retained." (PMID 35864317, 2022). "IHC staining of mesothelioma related markers including BAP1, EMA, Thrombomodulin (CD141), WT1, Podoplanin (D2-40), Calretinin and Cytokeratin6 (CK-6) revealed increased protein expression in 2175, 1187 or 1157 3D spheroids when compared to their 2D counterparts." (PMID 36091141, 2022). "The WT1-TCR iCD8αβ T-cells proliferated by Ff culture method were also able to control disease progression and showed survival benefit in a xenograft model that had been inoculated with a mesothelioma cell line, NCI-H226." (PMID 33462228, 2021). "The commonly used mesothelioma markers such as Calretinin and WT-1 are not useful to identify mesothelioma from mesothelial hyperplasia." (PMID 34956905, 2021).
mesothelioma (continued). "In this study it was reported that 93% of the mesotheliomas were found to be positive for WT1, while none of the carcinomas showed WT1 reactivity, pointing to WT1 as a very good positive marker for mesothelioma." (PMID 30965570, 2019). "The epithelial component of the biphasic mesothelioma retains positivity for AE1/AE3, CK5/6, calretinin and nuclear WT1, while sarcomatoid areas may lose these markers." (PMID 29621151, 2018). "For example, despite its immunogenic potential of wilms’ tumor protein 1 (WT1) in mice and clinical trials, our data indicated that a WT1-based vaccine was not able to induce potent CD8+ T cells to either prevent or cure WT1-expressing mesothelioma." (PMID 26431275, 2015). "Not surprisingly, our data showed that WT1 and D2-40 remained highly specific for mesothelial lineage, and should be included in the panel to differentiate mesothelioma from CC." (PMID 24860692, 2014). "There is some histological overlap with malignant mesothelioma as more than 50% of SS stain with calretinin; however, unlike mesothelioma, they are usually Ber-Ep4 positive and WT1 negative." (PMID 23984145, 2013). "D2–40 and WT1 are positive in mesothelioma; however, in our case, D2–40 and WT1 were negative." (PMID 40600206, 2025). "The importance of these findings, besides stratification according to survival, is that there is an apparent subgroup of BAP1 loss patients that will not respond to chemotherapy at all, given that both WT1 and calretinin both are negative, a “triple-negative” subtype of mesothelioma (5/5 patients)." (PMID 38280040, 2024). "Additionally, immunostaing for Wilm’s tumor 1 (WT1) was performed to definitively exclude mesothelioma, and the result was negative." (PMID 38105775, 2023). "Pleura-based tumor spread was indeed reminiscent of mesothelioma; however, diffuse expression of p40, MOC31, and claudin 4 and negative expression of WT1 and D2-40 ruled out this possibility." (PMID 29625594, 2018). "CD31 in fact is a marker of vascular lineage, more sensible and specific than CD34, WT1, FVIII, and it is almost always negative in non-vascular neoplasms, such as mesotheliomas and carcinomas." (PMID 28810922, 2017). "Some key tumor immunohistochemical markers (e.g., positive calretinin, CK7, and WT-1, with negative CEA) and cellular characteristics (epithelioid, poorly differentiated) are commonly seen for both mesothelioma and PSC." (PMID 24910640, 2014). "WT1 and calretinin are frequently negative, which helps to distinguish PPSS from mesothelioma." (PMID 40718269, 2025). "Should WT1 and/or D2-40 stain be not interpretable due to technical issues or limitations (such as a fallen section), one must use other mesothelial markers to rule out the tumors with calretinin and CK5/6 reactivity from mesothelioma, such as CC as shown in this study." (PMID 24860692, 2014).
melanoma (54 papers, 2007 to 2025). A malignant, usually aggressive tumor composed of atypical, neoplastic melanocytes. "This generation notably incorporated TAAs such as peptides from melanoma-associated antigens, Wilms tumor 1 (WT1), New York esophageal squamous cell carcinoma 1 (NY-ESO-1), and even whole tumor cell lysates." (PMID 39062753, 2024). "In melanoma, WT1 expression was implicated as a differentiating marker between tumor and normal melanocytic nevi." (PMID 38308491, 2024). "The overexpression of the WT1 protein has been associated with the occurrence of melanoma." (PMID 36960966, 2023). "Although WT1 could be expressed by Spitz naevi and in up to one third of dysplastic naevi, it is considered as a diagnostic tool in melanoma diagnosis." (PMID 32850962, 2020). "In this regard increased expression of WT1 is associated with the development and progression of different human cancers, including carcinomas of the lung, breast, colon, pancreas, desmoid tumors, hematopoietic system tumors, rhabdomyosarcoma, myofibroblastoma, melanoma and brain tumors." (PMID 25474318, 2014). "Silencing WT1 resulted in decreased zyxin expression, leading to reduced proliferation of melanoma cells." (PMID 38712343, 2024). "In xenograft models of melanoma and lung cancer, WT1 expression was found in the host vasculature and stroma invading the tumor, and WT1 deletion led to impaired tumor growth and metastasis." (PMID 38929778, 2024). "For example, the nebulization of PEI carrying Wilm’s tumor gene 1 (WT1-siRNA) has shown promise in the treatment of melanoma lung cancer metastasis, which can effectively attenuate tumor progression." (PMID 39199292, 2024). "In some investigations, PEI has been employed as a carrier to encapsulate Wilms’ tumor gene 1 (WT1-siRNA) for the treatment of melanoma lung cancer metastasis." (PMID 39199292, 2024). "GW0742-activated PPARβ/δ also inhibits the proliferation of different melanoma cell lines via its inhibition of Wilms tumor suppressor (WT1) promoter and direct transcriptional inhibition of its downstream target genes." (PMID 37251321, 2023). "In bone marrow stem cells, megakaryocytic differentiation is driven by the transcription factor WT1, and αIIbβ3-positive human melanoma cells express significant levels of WT1." (PMID 36754910, 2023). "No molecular tests were performed for this case, but further immunohistochemical analysis revealed that the dedifferentiated part was positive for CD56 and WT1, thus supporting the diagnosis of melanoma." (PMID 37373134, 2023). "Their research focused on a lysine-arginine rich peptide, WT1-pTj, derived from WT1’s zinc finger domain, evaluating its potential to work as a vaccination strategy in harnessing an antitumor-specific immune response against melanoma." (PMID 37725261, 2023). "They explored the therapeutic potential of targeting the Wilms tumor protein 1 (WT1) transcription factor in malignant melanoma." (PMID 37725261, 2023). "This work offers an expanded vision of the diverse mechanisms that participate in the process of malignancy of the melanoma cell line B16F10 that are dependent on WT1." (PMID 36960966, 2023). "Beyond in vitro results, WT1-pTj also revealed effectiveness in the in vivo context, curbing both metastatic and subcutaneous growth of murine melanoma in syngeneic mice, and enhancing survival rates in nude mice with human melanoma cells." (PMID 37725261, 2023). "We seeded melanoma cells over a cover slide and incubated with WT1 siRNA for 72 h, then processed the samples for TUNEL fluorescent assay." (PMID 36960966, 2023). "In this study, we evaluated the effects of silencing the WT1 protein by siRNA in both in vitro in the B16F10 melanoma cell line and in vivo in a murine model of lung metastatic melanoma." (PMID 36960966, 2023). "Our first objective was to evaluate the efficacy of our WT1 siRNA to silence the expression of the WT1 protein in the B16F10 melanoma cell line." (PMID 36960966, 2023).
melanoma (continued). "To elucidate the importance of WT1 in the cell cycle progressions, we incubated the melanoma cells with WT1 siRNA for 72 h." (PMID 36960966, 2023). "In this instance, WT1 is a promissory therapeutic target as it is overexpressed in many human cancers, including the transformation from normal melanocytes to melanoma." (PMID 36960966, 2023). "PPARβ/δ activation inhibits melanoma-cell proliferation via the direct repression of WT1, while WT1 stimulates melanoma-cell proliferation." (PMID 35954274, 2022). "Currently, Wilms’ tumor 1 (WT1), preferentially expressed antigen in melanoma (PRAME), and minor histocompatibility antigens (MiHA) have been the only AML antigens targeted using TCR-T cells in a clinical setting." (PMID 34572745, 2021). "Regarding the Wilms’ tumor suppressor WT1, we showed that PPARβ/δ activation in melanoma cells inhibits its expression via direct transcriptional repression." (PMID 32375405, 2020). "PPARβ/δ activation using GW0742 or GW501516 inhibited proliferation of different melanoma cell lines, which was due to direct transcriptional repression of the Wilms’ tumor suppressor WT1 and its downstream target genes zyxin and nestin." (PMID 32375405, 2020). "Other tumors on the differential, metastatic lung cancer, mesothelioma, melanoma, and primary adrenal gland tumor, were excluded by negative staining of tumor cells for TTF-1, napsin, calretinin, WT-1, pan-melanoma, SOX10, and synaptophysin." (PMID 32983683, 2020). "Vaccination of the mice with gp100 (outside) and WT1 (inside) peptides loaded on the BC-PIV envelope suppressed melanoma growth with CD8+ tumor-infiltrating lymphocytes." (PMID 31501502, 2019). "In melanoma, in vitro WT1 silencing resulted in decreased cell proliferation, followed by apoptosis induction with caspase-3 activation, while in vivo it reduced the melanoma metastatic to lungs." (PMID 28458685, 2017). "On the other hand, some studies indicate that pharmacologic activation of PPARδ by its agonists (GW0742 and GW501516) inhibited proliferation of the murine melanoma cells, accompanied by downregulation of WT1." (PMID 28458685, 2017). "Recently, functional in vitro studies showed that WT1 silencing through an antisense oligomer results in growth inhibition in different cancer cell lines, including breast, lung, melanoma, glioblastoma, as well as various types of solid tumors cell lines." (PMID 25474318, 2014). "Cells, transfected either with MT1-Mc1r or WT1-Mc1r 24 hours before injection, were injected into tail veins of multiple recipient mice, and lungs were harvested and examined visually for melanoma clones after 18 days." (PMID 22363655, 2012). "From the siRNAs tested in vitro, we selected WT1-Mc1r which was the highly effective in down-regulating Mc1r expression and melanoma migration." (PMID 22363655, 2012). "Once we confirmed the efficacy of silencing WT1 as a mechanism to diminish the malignancy phenotype in vitro, we wanted to further expand the application of this siRNA therapy on an animal model bearing melanoma metastases on the lungs." (PMID 36960966, 2023). "Our L-siRNA could be delivered to the lungs with simple administration, achieving the silencing of the WT1 oncogene, and obtaining a significant therapeutic effect over the melanoma metastases on the lungs of our animal model." (PMID 36960966, 2023). "For ambiguous cases, other markers such as WT1 or PRAME help confirm melanoma diagnoses." (PMID 37373134, 2023). "After confirming that we could achieve a potent silencing effect of WT1 with our siRNA sequence, we sought to analyze if this protein was involved in conferring a metastatic phenotype to the melanoma cells by changing its motility properties." (PMID 36960966, 2023).
melanoma (continued). "Conversely, corroborating the results of the current investigation, melanoma and lung cancer xenograft models express WT1 immunoreactivity at the level of tumor invading stromal and vascular elements, but not at the level of similar proximal tumor-adjacent blood vessels/stroma." (PMID 35453662, 2022). "In addition, BC-PIV with antigenic epitopes of both melanoma gp100 and WT1 tumor antigen induced a CD8+ T-cell-mediated response in tumor-transplanted syngeneic mice." (PMID 31501502, 2019). "In addition, the established T-cell manufacturing protocol can be easily adapted to enrich T cells restricted against other pathogens such as EBV, ADV, HHV6 and Aspergillus and can be extended to melanoma (Melan-1/Mart-1) and tumor antigens (WT1)." (PMID 25510656, 2014). "Among various peptide vaccines, the notable targets are Wilms’ tumor 1 (WT-1) antigen, proteinase-3+ neutrophil elastase (PR-1), NY-ESO-1 peptide, preferentially expressed antigen of melanoma (PRAME) and receptor for hyaluronic acid-mediated motility (RHAMM)." (PMID 38191498, 2024). "Antigens such as Wilms’ tumor 1 (WT1), preferentially expressed antigen of melanoma (PRAME), and human telomerase reverse transcriptase (hTERT) have been used as LAAs for Mo-DC loading." (PMID 35074008, 2022). "The silencing of WT1 through shRNAi has a synergistic effect with doxorubicin and cisplatin, sensitizing B16F10 melanoma cells." (PMID 32850962, 2020). "EWS is fused to ATF1 (activating transcription factor 1) in malignant melanoma of soft parts, WT1 (Wilms tumor 1) in intra-abdominal DSRCT, CHOP in myxoid liposarcoma, and CHN in myxoid chondrosarcoma." (PMID 20924475, 2010). "In addition to WT1 epitopes, TCRGP models were trained against CMV, IAV, EBV, SARS-CoV-2 and melanoma-related epitopes and achieved mean AUROC and AUPR values of 0.82 ± 0.08 and 0.58 ± 0.18, respectively." (PMID 40847198, 2025). "They found that in malignant melanoma, over 80% of cells express WT1, while it is not expressed in normal skin or benign nevi." (PMID 38712343, 2024). "As S100, WT1, and CD99 may be expressed in both melanomas and various sarcomas, SOX10 was particularly useful in diagnosing this osteoid melanoma." (PMID 37373134, 2023). "In our previous studies, the B16/murine MHC knockout/HHDII+/DR1+ murine melanoma cell line was shown to constitutively express the murine WT1 protein (data not shown)." (PMID 34262856, 2021). "Indeed, WT1 is expressed in more than 80% of malignant melanoma cells, but not in normal skin or benign melanocytic nevi." (PMID 32850962, 2020). "myogenic differentiation 1 (MYOD1), desmin, wilms tumor 1 (WT1), CD57,transducin-like enhancer of split 1 (TLE1), melanoma/prostate markers, chromogranin A, andinhibin were negative." (PMID 34106022, 2021). "All other markers tested were negative (pan-melanoma, HMB45, Melan A, keratin AE1/AE3, desmin, alpha smooth muscle actin, h-caldesmon, CD34, p16, CD117, DOG1, myogenin, CD10, estrogen receptor (ER), progesterone receptor (PR), PAX8, WT1, synaptophysin, chromogranin A, CD99 and PRAME))." (PMID 39196362, 2024).